ENSG00000258691 (novel protein)
Gene: Protein-coding gene on chromosome 14 (96,204,844 to 96,263,929, forward strand). Ensembl gene ENSG00000258691.
Genetic constraint (gnomAD): Loss-of-function variants: 7 observed, 4.73 expected, observed/expected ratio (o/e) 1.48, 90% interval 0.79 to 1.93. That is too few expected variants to judge how well the gene tolerates losing a copy. Missense variants: 51 observed, 47.14 expected, observed/expected ratio (o/e) 1.08, 90% interval 0.86 to 1.37. Synonymous variants: 15 observed, 16.44 expected, observed/expected ratio (o/e) 0.91, 90% interval 0.61 to 1.4.